LINC00887 (long independently transcribed non-coding RNA 887)
Synonyms: linc-ATP13A4-8; HEIRCC; ACLY-BP; LINC02036
Gene: Long non-coding RNA gene on chromosome 3 (194,200,261 to 194,324,520, reverse strand). Ensembl gene ENSG00000214145.
Diseases named in the same sentence as LINC00887 in open-access papers:
LINC00887 is named in the same sentence as 10 diseases in open-access papers, as found by Europe PMC text mining. Sharing a sentence is not in itself a finding about the gene and the disease. The quoted sentences say what the papers report.
renal cell carcinoma (4 papers, 2017 to 2024). "LINC00887, a long non‐coding RNA, is overexpressed in renal cell carcinoma (RCC) tissue and the sera of RCC patients." (PMID 32654370, 2020). "In addition, it has been reported that linc00887 plays an important role in nasopharyngeal carcinoma, non-small cell lung cancer and renal cell carcinoma, but the role of linc00887 was largely unknown in cervical cancer." (PMID 33413358, 2021).
nasopharyngeal carcinoma (3 papers, 2021 to 2024). A carcinoma arising from the nasopharyngeal epithelium. "LINC00887 expression is also upregulated in nasopharyngeal carcinoma, and overexpression of LINC00887 can significantly accelerate proliferative ability of nasopharyngeal carcinoma cells." (PMID 36060659, 2022).
cervical cancer (2 papers, 2021 to 2024). A primary or metastatic malignant neoplasm involving the cervix. "In contrast, LINC00887 was downregulated in cervical cancer and its overexpression suppressed the proliferation and invasion." (PMID 38338866, 2024). "In order to investigate the roles of linc00887 in the progression of cervical cancer cells, Hela or C33A cells were transfected with pcDNA-linc00887 to increase or decrease linc00887 level." (PMID 33413358, 2021). "In order to further understand the mechanism of linc00887 regulating the progression of cervical cancer, we detected effect of linc00887 on the expression of key proteins in FRMD6-Hippo signaling pathway." (PMID 33413358, 2021). "Here, we demonstrated that linc00887 was remarkably down-regulated in human cervical cancer tissues or cell lines." (PMID 33413358, 2021). "The results showed that linc00887 level was also downregulated in cervical cancer cell lines, especially in HeLa and C33A cell lines, compared with normal cervical cell lines (Ect1/E6E7) (p < 0.05)." (PMID 33413358, 2021). "In conclusion, these findings indicated that Linc00887 sponging miR-454-3p inhibited the progression of cervical cancer through activating FRMD6-Hippo axis signaling pathway." (PMID 33413358, 2021). "In order to investigate the role of linc00887 in cervical cancer, we detected the linc00887 level in human cervical cancer tissues and cell lines." (PMID 33413358, 2021). "Subsequent functional experiments confirmed that linc00887 reversely regulates miR-454-3p level, and the re-expression of miR-454-3p can reverse the inhibition of linc00887 on cervical cancer." (PMID 33413358, 2021). "Our results confirmed that linc00887 negatively regulated cell proliferation and invasion in cervical cancer." (PMID 33413358, 2021). "Linc00887 was downregulated in cervical cancer tissues or human cervical cancer cell lines (Hela, C33A) compared with normal tissues or cell lines." (PMID 33413358, 2021). "In contrast, LINC00887 was downregulated in cervical cancer." (PMID 38338866, 2024). "Our results suggested that linc00887 might be a new biomarker in cervical cancer progression." (PMID 33413358, 2021).
glioma (2 papers, 2022 to 2024). A benign or malignant brain and spinal cord tumor that arises from glial cells (astrocytes, oligodendrocytes, ependymal cells). "For example, LINC00887 expression is upregulated in glioma, and knocking out LINC00887 can inhibit the proliferation of cancer cells." (PMID 36060659, 2022).
lymph node metastasis (1 paper, 2020). "Moreover, LINC00887 expression was significantly elevated in the serum of both RCC patients with and without lymph node metastasis compared to healthy subjects, whereas there was no significantly different for serum between lymph node‐metastatic and non‐metastatic patients." (PMID 32654370, 2020).
ovarian carcinoma (1 paper, 2024). A malignant neoplasm originating from the surface ovarian epithelium. "However, there are no reports of ovarian cancers expressing CBR3‐AS1, LINC00887, and TSIX; this is the first report of their expression in ovarian cancers, including HGSC." (PMID 38571514, 2024).
cancer (3 papers, 2017 to 2024). A tumor composed of atypical neoplastic, often pleomorphic cells that invade other tissues. "In summary, LINC00887 is involved in critical processes that are important for the initiation and progression of cancer." (PMID 38338866, 2024). "Although these studies indicate the key role of LINC00887 in cancer development, no literature has explored LINC00887 and its role in ccRCC immunity." (PMID 36060659, 2022).
tumor (2 papers, 2017 to 2021). "The result of RT-qPCR showed that the expression of linc00887 was downregulated in tumor tissues compared with normal tissues (p < 0.01)." (PMID 33413358, 2021).
LINC00887 also shares sentences with these, for which no sentence is quoted: lung carcinoma (1 paper); non-small cell lung carcinoma (1).